MIR2115 (microRNA 2115)
Synonyms: hsa-mir-2115
Gene: MicroRNA gene on chromosome 3 (48,316,360 to 48,316,459, reverse strand). Ensembl gene ENSG00000252466.
Homologues: Orthologues: chimpanzee MIR2115 (100% identical).